SSTR2 (somatostatin receptor 2)
Diseases named in the same sentence as SSTR2 in open-access papers (continued):
Sharing a sentence is not in itself a finding about the gene and the disease.
tumor (continued). "Furthermore, SSTR2 gene expression in the ONB tumor samples was considerably higher than that in a cohort of gastrointestinal NET tumor samples, for which the SSTR2-directed radioactive Lutetium (177Lu-DOTATATE) is a U.S. Food and Drug Administration-approved therapy." (PMID 39682120, 2024). "Besides FDA-approved radiopharmaceuticals for theranostic targeting of SSTR2 and norepinephrine transporters in NENs, a broad range of theranostic agents using other radionuclides or directed towards other tumor-specific molecular targets are currently under preclinical and clinical evaluation." (PMID 38164150, 2024). "Furthermore, higher-grade tumor tissues were devoid of SSTR2 expression." (PMID 38203605, 2023). "Moreover, our findings suggest that PanNET tumor cells can produce higher amounts of resident hsa-miR-5096 downmodulating SSTR2 with autocrine mechanism or shedding increased amounts in biofluids via exosomes, resulting in SSTR2 expression in recipient cells via a paracrine mechanism." (PMID 37287922, 2023). "Consistent with radioligand uptake in vitro a more pronounced anti-tumor effect in vivo was associated with attenuated [64Cu]Cu-DOTA-TATE uptake in MPC allograft mice, indicating that cytotoxic effects of the epigenetic drugs outweigh stimulatory effects on SSTR2 content." (PMID 36593963, 2023). "Additionally, our results suggest that SSTR2 contributes to tumor immunity." (PMID 37900156, 2023). "Studies suggest that SSTR2 may be a strong mediator of tumor growth." (PMID 37568733, 2023). "In addition, SSTR2 expression decreases with increasing malignancy and tumour stage." (PMID 36980746, 2023). "As SSTR2 PET and its associated ligands become more cost-effective and can be offered on a widespread basis, a reduction in the frequency of postoperative surveillance scans via MRI considering its limitations in predicting tumor recurrence has to be evaluated." (PMID 37642702, 2023). "Additionally, researchers found that binding of SST and SSTR2 could inhibit immune cells cytokine release and have an effect on the tumor microenvironment (TME)." (PMID 35264912, 2022). "This pilot study was designed to test the following assumptions: (i) SSTR2 expression in SI-NETs correlates among a patient’s lesions, i.e., the presence of one tumor with a low SSTR2 expression indicates that the patient could have other lesions with a low SSTR2 expression." (PMID 33922482, 2021). "The ability of SSTR2 agonists to control NPC tumor growth is unknown." (PMID 33402692, 2021). "This may explain the differences in SSTR2 and -5 expression in relation to tumor subtype." (PMID 34830858, 2021). "Thus, tumours with low SSTR2 expression commonly display poor response to SSAs treatment." (PMID 30843342, 2019). "In addition, the differences in SSTR2 methylation level were not statistically associated with age, smoking behavior, histological differentiation or clinical stage in tumor tissues or paired tissues (all adjusted P > 0.05, data not shown)." (PMID 26796520, 2016). "Besides tumour perfusion and inhomogeneous distribution of SSTR2, tumour size, vessel density, permeability and tumour growth doubling time can play a critical role for the success of PRRT; this is especially true for α-emitters, where the penetration depth in tissue is relatively short (50–100 μm)." (PMID 26791386, 2016). "In our case, immunostaining showed positive results for CgA, Syn, CD56, SSTR2, INSM1, CK and Ki-67, consistent with the histopathologic examination, confirming the neuroendocrine nature of the tumor." (PMID 40034377, 2025). "Given the expression of somatostatin receptors (SSTRs) by tumor cells in MCC, SSTR PET can also be considered, with tracers such as 68Ga-DOTATATE and 68Ga-DOTATOC binding to the SSTR2 subtype with particularly high affinity." (PMID 41210275, 2025).
tumor (continued). "DEX treatment of a murine corticotroph tumor cell model, AtT20, increased miR-375 expression, analysis of which revealed a seed sequence for Sstr2, supporting the hypothesis that GCs excess might downregulate SSTR2 expression even through an epigenetic mechanism." (PMID 40488558, 2025). "Our results confirmed good agreement between in vivo tumor uptake with SSA-PET/CT and in vitro SSTR2 expression with IHC, highlighting the potential of using IHC for clinical decision-making in NEN patients when SSA-PET/CT is not available." (PMID 40724801, 2025). "High SSTR2 expression provides the biological rationale for using 68Ga-labeled somatostatin analogs, such as DOTATATE, in PET/CT imaging, enhancing tumor detection and characterization." (PMID 40869136, 2025). "SST exerts direct anti-tumor effects by direct binding to and activation of one or more of five different SST receptors (SSTR1-5), with SSTR2 representing an inhibitory G protein-coupled receptor." (PMID 40134804, 2025). "Murine xenograft models likewise displayed higher tumor-to-background ratios on [68Ga]Ga-DOTATATE PET after everolimus, consistent with drug-induced SSTR2 gene upregulation." (PMID 41210247, 2025). "Conversely, recurrent-tumours (more aggressive than primary-tumours) showed higher SSTR1 and/or SSTR2 levels." (PMID 40268793, 2025). "The overexpression of SSTR2 supports SSA efficacy in controlling hormonal syndromes and stabilizing tumor growth." (PMID 39996718, 2025). "Tumor cells exhibited weak EMA expression and focal positivity for PR, with strong, diffuse staining for SSTR2 and vimentin." (PMID 41013491, 2025). "In vivo studies have shown that ectopic SSTR2 expression in PDAC cells, e.g., human BxPC-3 or hamster PC-1.0 cells, can induce anti-tumor bystander effects." (PMID 40134804, 2025). "Collectively, these insights highlight the importance of further investigations to elucidate the role of SSTR2 in cancer metastasis in HCC and to explore its potential as a therapeutic target to inhibit tumor invasion in this highly fatal malignancy." (PMID 41002582, 2025). "Percutaneous liver biopsy confirmed metastatic neuroendocrine tumor, with tumor cells positive for PCK (+), CD56 (+), Syn (+), CgA (+), SSTR2 (+) and a Ki-67 index of ∼2%." (PMID 41210247, 2025). "Next-generation SSTR2 and PSMA theranostic targeting vectors hold potential to further improve antitumor efficacy through improved tumor uptake and reduced uptake in off-target tissues." (PMID 39479448, 2024). "The cytotoxicity studies revealed a significant finding; namely, the targeted delivery system most effectively inhibited tumor growth in CFPAC-1 cells, aligning with the cell line’s high SSTR2 expression levels." (PMID 38791582, 2024). "The expression of SSTR2 in ONB and SNEC has been reported across tumor grades and in both primary and metastatic sites; its expression in SNUC appears to be less clear." (PMID 39682120, 2024). "SSTR2 and -5 do not only represent established markers of NED but also possess tumor-relevant functions." (PMID 39682758, 2024). "PSC-PEG2-TOC (VMT-α-NET) is a somatostatin receptor subtype 2 (SSTR2) targeting peptide of very high stability for the treatment of neuroendocrine tumours (NET) that shows rapid tumour accumulation, high tumour retention and fast renal excretion." (PMID 39604560, 2024). "Immunohistochemistry of the tumor revealed positivity for epithelial membrane antigen (EMA) and somatostatin receptor-2 (SSTR-2), with a Ki-67 (MIB-1) labeling index of 5%." (PMID 39868379, 2024). "Lanreotide autogel/depot as a long-acting SSA binds with high affinity to type 2 somatostatin receptor (SSTR2) and SSTR5, suggestive of a role in the inhibitory effect of lanreotide on tumor cell proliferation and hormone secretion." (PMID 39272962, 2024). "As mentioned in the previous sections, Merkel carcinoma cells preferentially express SSTR2 and SSTR5, meaning that in theory octreotide must be effective in such neoplasias." (PMID 39329930, 2024).
tumor (continued). "We also examined changes in serum tumor markers and inflammatory factors in Th-NET patients, presenting the expression status of SSTR2 and MGMT in pathological evaluations, thereby filling a significant data void in Th-NET research." (PMID 39061142, 2024). "Lanreotide binds and activates SSTR2 and SSTR5, leading to the inhibition of the production of substances that support tumor growth and inducing cell arrest." (PMID 38473389, 2024). "A tissue analysis of the biopsies collected throughout the course of the disease revealed heterogeneous drug target expression of somatostatin receptor 2 (SSTR2) across and within tumor lesions." (PMID 39324010, 2024). "Histochemistry analysis of the tumor revealed positive staining for TSH, growth hormone (GH), prolactin (PRL), luteinizing hormone (LH), and somatostatin receptor 2 (SSTR2)." (PMID 38516415, 2024). "In all specimens, CHGA, SSTR2, and SYP exhibited strong staining in the (ductal) epithelial tumor cells." (PMID 39682758, 2024). "Our results demonstrate significant upregulation of SSTR2 surface expression and 177Lu-DOTATATE uptake after HDACi treatment in QGP-1 tumor xenografts." (PMID 37487000, 2023). "Targeting SSTR2 with the miniaturized drug conjugate PEN-221 leads to cell-cycle arrest and apoptosis, resulting in tumor regression in multiple SCLC SSTR2-expressing human xenograft models." (PMID 38203275, 2023). "In those patients with available remnant tumor samples, we explored the association between tumor immunostaining for E-cadherin and SSTR2 with sAOT results: 24 and 18 patients, respectively (15 responders and 9 non-responders for E-cadherin and 12 responders and 6 non-responders for SSTR2)." (PMID 38027102, 2023). "Our study results show that pretreatment with HDACis increase SSTR2 surface expression in vitro and in vivo, resulting in increased 177Lu-DOTATATE tumor uptake." (PMID 37487000, 2023). "SSTR2 immunostaining was strong and diffuse in seven of the eight tumours, and SSTR5 was present in seven tumours although intensity of staining was weak." (PMID 37851558, 2023). "When H-69 SCLC cell line xenografts expressing mRNA for SSTR2 were introduced in nude mice and subsequently treated with an SST analogue AN-238, tumour growth was inhibited." (PMID 38203605, 2023). "Our results showed that SSTR2 induction and [64Cu]Cu-DOTA-TATE binding occurred to a lesser extent in tumor-bearing mice compared to cell cultures." (PMID 36593963, 2023). "Gene expression levels of SSTR2 and SSTR5 within hPITO28 and 34 correlated with protein levels within the patient’s tumor tissue." (PMID 36359740, 2022). "However, as the tumor progressed to higher histological grades, possibly in conjunction with genetic/epigenetic alterations such as the SSTR2 promoter hypermethylation, foregut NETs could be more deviated from the normal counterparts (right blue arrow) and demonstrate lower SSTR2 expression." (PMID 35159042, 2022). "Both drugs act as somatostatin analogues with a high affinity for somatostatin-receptor type 2 (SSTR2) and to a lesser extent for SSTR5, inhibiting GH release from pituitary cells and preventing tumor growth." (PMID 35744057, 2022). "SSTR2/SSTR3 mediated cell proliferation and apoptosis has also been proved to understand the molecular interactions involving SSTRs in tumor biology." (PMID 35053382, 2022). "For instance, 111In-DOTA-NOC has increased affinity towards SSTR3 and 5, along with a high affinity to SSTR2, thus potentially allowing for further optimization of SSA-based tumor imaging." (PMID 35712243, 2022). "In this manuscript, we report the radiolabeling and early biological evaluation of [153Sm]Sm-DOTA-TATE in SSTR2-expressing CA20948 cells and tumor models of pancreatic neuroendocrine cancers." (PMID 36559060, 2022). "For instance, the antitumor efficacy of ADC that targets SSTR2 was evaluated in a mouse xenograft model implanted with BON-1 human NET cells, in which it reduced tumor growth." (PMID 35628495, 2022).
tumor (continued). "Previously, we have demonstrated the utility of somatostatin receptor 2 (SSTR2) for CAR T cell imaging, illustrating the expansion and contraction of CAR T cells in tumor as well as off-tumor expansion." (PMID 36463361, 2022). "We tested the SSTR2‐targeting and imaging properties of the resulting probe 68Ga‐DOTA‐ICC‐TATE in vitro and in a tumor xenograft mouse model." (PMID 33238069, 2021). "In vivo anti-tumor efficacy showed that the anti-SSTR2 ADC with doses of 8 and 16 mg/kg body weight effectively inhibited tumor growth." (PMID 34063284, 2021). "Intriguingly, the estimated SSTR2 densities in kidneys (3.52 ± 0.07 nmol/L) and tumor (11.7 ± 3.0 nmol/L) in AR42J-tumor bearing mice were in the reported ranges of renal (2.3–7.1 nmol/L) and tumor (7–16 nmol/L) SSTR2 densities in humans." (PMID 34959413, 2021). "The expression of SSTR2 and SSTR5 varied significantly between tumor subtypes (p < 0.001 and p = 0.003, respectively)." (PMID 34830858, 2021). "A novel higher selective monoclonal antibody for extracellular domain of SSTR2 binds the surface of neuroendocrine tumor (NET) cells via signalling cascades and reduce tumor growth." (PMID 33796080, 2021). "Our dye‐bridged hybrid probe showed excellent in vitro SSTR2‐affinity and peptide functionality, whereas the in vivo PET imaging using 68Ga at an early imaging time point needs further improvements for higher tumor‐to‐background ratios." (PMID 33238069, 2021). "For the cohort in which treatment began 4 weeks after tumor inoculation, [64Cu]Cu-SARTATE PET/CT imaging of selected mice from each treatment group was carried out in week 3 and confirmed SSTR2-positive NB tumors." (PMID 33630166, 2021). "Differences related to tumor grade were evident for SSTR1 (p = 0.036), SSTR2 (p = 0.009) and SSTR5 (p = 0.029), while differences for SSTR3 (p = 0.059) were non-significant." (PMID 34830858, 2021). "In contrast, the D341 model, which showed similar SSTR2 expression and GaTate uptake to that of the AR42J model, was highly sensitive to LuTate with complete tumour regression observed for 65 days." (PMID 32576907, 2020). "The in vitro and in vivo evaluation of SSTR2/CXCR4 mAbs-EV-Ver-A/DM1 showed high NET-specific targeting and high efficacy to inhibit tumor growth in xenograft mouse model." (PMID 33187322, 2020). "Remarkably, two doses of 2 mg/kg PEN21 were enough to cure H524MD lung cancer tumours (SSTR2-expressing), whereas two doses of 1 mg/kg were needed to cure HCC33 tumours." (PMID 31544868, 2018). "In this study, the expression of mRNA for SSTR-2 was studied in 46 UM specimens, and SSTR-5 in 9 UM tumor samples." (PMID 29949880, 2018). "Significant reduction in C6 tumor volumes in rat flanks were observed upon SSTR2 PEP-FITC-NP treatment, whereas in untreated groups the tumor volume increased considerably." (PMID 29029435, 2017). "In the metastasis-containing lymph node samples, SSTR2 and CXCR4 were strongly expressed in germinal centers of (activated) lymph follicles in close proximity to the tumor cells." (PMID 29282035, 2017). "To verify the therapeutic effects of targeting SSTR2 with 177Lu-DOTA-TATE, we treated CHLA-15 tumor-bearing mice with 177Lu-DOTA-TATE at the dose of 20 MBq/animal." (PMID 29097943, 2017). "The monoclonal antibodies against SSTR1, SSTR2, SSTR3, SSTR5, and CXCR4 produced distinct immunostaining of the plasma membrane, but also of the cytoplasm of the HCC and CCC tumor cells." (PMID 29282035, 2017). "Comparing relative receptor expression intensities between the two tumor entities, CCCs showed significantly higher intensities of expression of SSTR1, SSTR2, SSTR5, and CXCR4 than HCCs." (PMID 29282035, 2017). "One of the five somatostatin receptors, SSTR2, can be detected to be expressed in tumor, and SSTA has much higher binding affinity to SSTR2 in tumor tissues than in normal tissues." (PMID 27825139, 2016).
tumor (continued). "On the contrary, Vt in the tumor was lower for 68Ga-DOTANOC than for the other two tracers, and although 68Ga-DOTANOC has higher affinity for SSTR2 than 68Ga-DOTATOC, it also has affinity for SSTR3 and SSTR5." (PMID 25369268, 2014). "Univariate analysis identified a significant correlation between SSTR2 and the response to the acute SA test, while SA treatment, RORC and DOK6 mRNA levels were correlated with tumor size." (PMID 23825587, 2013). "Lanreotide is an octapeptide analog of endogenous somatostatin with a high affinity for somatostatin receptor 2 (SSTR2), which is overexpressed in many tumor types." (PMID 24300405, 2013). "The coupling of potent chemotherapeutic agents to SSTR2-selective somatostatin analogs has provided new cytotoxic SRIF-conjugates that selectively target SSTR2-specific sites, displaying significant anti-tumor abilities in many different types of tumors." (PMID 24287991, 2013). "Multiple stepwise linear regression identified SSTR2, TIMP1 and KCNIP3 as predictors of the response to the acute SA test and SA treatment and RORC as a predictor of tumor size." (PMID 23825587, 2013). "Several previous studies have shown the expression of one or more SSTRs including SSTR2 and SSTR5 in tumor tissues of different origins like breast, prostate, pituitary and pancreas." (PMID 24281555, 2012). "The high density of SSTR2 in endocrine tumours explains the use of SSTR 2 specific analogues in the diagnosis and treatment of these tumours." (PMID 20196864, 2010). "Most of cancer biopsies showed different tumor grade zones; SHP-1 and SSTR2 immunostaining were analyzed for each zone and showed different intensities in comparisons with the control." (PMID 19365586, 2009). "Reportedly, the cultured tumor cells IMR32 and CFPAC-1 highly express some SSTRs, with BON cells natively expressing high levels of SSTR1, SSTR2 and SSTR5." (PMID 21892324, 2008). "HCC patients with elevated SSTR2 expression may be ideal candidates for 68Ga-DOTATATE PET/CT imaging, a molecular imaging modality that can provide superior tumor detection, evaluate treatment response, and guide patient stratification for targeted therapies." (PMID 41002582, 2025). "Among the analysed tumours, nine (69.23%) displayed either no or extremely low cytoplasmic staining, while four tumours (30.77%) showed low cytoplasmic immunoreactivity (< 85% of tumour cells expressing SSTR2)." (PMID 40268793, 2025). "Novel immunotherapies, including bispecific T-cell engagers, tumor-infiltrating lymphocytes (TILs), and CAR-T cells targeting neuroendocrine-specific antigens such as SSTR2 or CEACAM5, remain in preclinical or early clinical phases, necessitating further validation of safety and efficacy." (PMID 40869136, 2025). "All lesions with missing or weak SSTR2 expression showed vital tumor cells and no specific radiation-induced morphologic changes (no necrosis, no bizarre nuclei) on histopathologic evaluation." (PMID 39819694, 2025). "Moreover, a similar distribution pattern was found for SSTR2 and the expression of key NPC markers in tumour cells." (PMID 40268793, 2025). "IHC analysis confirmed SSTR2 expression in tumor sections from HCC xenografts along with the absence of the target in HCT116 tumors." (PMID 39857944, 2025). "Remarkably, when selecting only the tumour cells in the dataset, we also observed a similar expression pattern in NPC signature (based on SOX2, NES, and ASCL1 genes) and SSTR2, supporting the putative relationship between this NPC population and SSTR2 levels." (PMID 40268793, 2025). "CYL-02 utilizes plasmid DNA containing genes for somatostatin receptor 2 (SSTR2), deoxycytidine kinase (DCK), and uridylate monophosphate kinase (UMK), which together aim to restore gene function in PDAC cells while also sensitizing the tumor to gemcitabine." (PMID 39518005, 2024).